GLI4 (GLI family zinc finger 4)
Synonyms: HKR4; ZNF928
Tractability: PROTAC: ubiquitination databases record sites on it.
Gene: Protein-coding gene on chromosome 8 (143,263,193 to 143,276,937, forward strand). Ensembl gene ENSG00000250571.
Subcellular location: Nucleus
Subcellular location (Human Protein Atlas): Cytokinetic bridge; Nucleoplasm
Gene Ontology:
Molecular function: protein binding; DNA-binding transcription factor activity, RNA polymerase II-specific; RNA polymerase II cis-regulatory region sequence-specific DNA binding
Biological process: regulation of DNA-templated transcription; regulation of transcription by RNA polymerase II
Cellular component: nucleus
Genetic constraint (gnomAD): Loss-of-function variants: 34 observed, 26.01 expected, observed/expected ratio (o/e) 1.31, 90% interval 0.99 to 1.73. The synonymous counts are far from expectation, so gnomAD's model fits this gene poorly and the ratio says little. Missense variants: 680 observed, 472.05 expected, observed/expected ratio (o/e) 1.44, 90% interval 1.35 to 1.53. Synonymous variants: 270 observed, 203.5 expected, observed/expected ratio (o/e) 1.33, 90% interval 1.2 to 1.47.
Homologues: Orthologues: chimpanzee GLI4 (99% identical), macaque GLI4 (96% identical), guinea pig GLI4 (77% identical), pig GLI4 (73% identical), rat Gli4 (66% identical). Paralogues in human: ZNF250 (43% identical), ZNF7 (43% identical), ZNF879 (43% identical), ZNF471 (43% identical), ZNF658 (43% identical), ZNF595 (42% identical), ZNF33B (42% identical), ZNF41 (41% identical), ZNF568 (41% identical), ZNF605 (41% identical), ZNF606 (41% identical), ZNF728 (41% identical), and 164 more.
Diseases named in the same sentence as GLI4 in open-access papers:
GLI4 is named in the same sentence as 9 diseases in open-access papers, as found by Europe PMC text mining. Sharing a sentence is not in itself a finding about the gene and the disease. The quoted sentences say what the papers report.
glioblastoma (3 papers, 2019 to 2023). The most malignant astrocytic tumor (WHO grade IV). "We demonstrated this hypothesis by overexpressing ETNPPL in 3 glioblastoma cell cultures (Gli4, Gli7, LGG85)." (PMID 32218467, 2020). "Also, our results show that the orientation of the NF governs the direction of migration of Gli4 cells much in the way that glioblastoma cells in vivo are guided by axon alignment in the CC." (PMID 31601895, 2019). "Second, we tested whether DNA‐PK is responsible for type I IFN responses in the absence of cGAS in glioblastoma cells by treating T98G, Gli4, and GSC9 with the NU7441 DNA‐PKcs inhibitor." (PMID 36574362, 2023).
glioma (2 papers, 2020 to 2023). A benign or malignant brain and spinal cord tumor that arises from glial cells (astrocytes, oligodendrocytes, ependymal cells). "We used two previously characterized glioma stem cell cultures (Gli4 and Gli7) which we derived from GBM-affected patients." (PMID 32218467, 2020).
Hypertension (1 paper, 2021). The presence of chronic increased pressure in the systemic arterial system. "Two genes each from LEAD vs. CVD comparison were found to be linked to hypertension status (GLI4 and MNDA) and usage of statins (FAM167A and C1orf216) as well as 58 genes (54 and 4 from LEAD vs. CVD and AAA vs. CVD comparisons, respectively) were related to acetylsalicylic acid medication." (PMID 33801150, 2021).
tumor (4 papers, 2012 to 2025). "We also found that calpain-2 is expressed by GliT cells staying inside the bulky tumour, while Gli4 cells migrating in the CC do not express calpain-2." (PMID 31601895, 2019). "GLI4, often described as an antagonistic factor, was overexpressed in 15.5% of tumour samples, but not significantly." (PMID 22361633, 2012). "Additionally, the negative correlation between GOLPH3 and GLI4, as well as AURKA, becomes significantly weaker in tumor samples." (PMID 40136480, 2025).
GLI4 also shares sentences with these, for which no sentence is quoted: cancer (2 papers); colorectal cancer (1); congenital hypopituitarism (1); retinoblastoma (1); synucleinopathy (1).